HRAS (HRas proto-oncogene, GTPase)
Diseases named in the same sentence as HRAS in open-access papers (continued):
Sharing a sentence is not in itself a finding about the gene and the disease.
anaplastic astrocytoma (1 paper, 2024). "In anaplastic astrocytoma, RAS mutations typically involve alterations in the HRAS, KRAS, or NRAS genes." (PMID 39459475, 2024).
astrocytomas (1 paper, 2024). "It is important to note that the molecular mechanisms underlying the relationship between genetic mutations, such as HRAS mutations, and the development of tumors, including astrocytomas, can be complex and may involve multiple factors." (PMID 39459475, 2024). "In this case of an adult woman with Schimmelpenning syndrome with an IDH-mutant astrocytoma, WHO grade 3, a mutation in the HRAS gene with 31% prevalence was found." (PMID 39459475, 2024).
autoimmune hepatitis (1 paper, 2022). Hepatitis caused by autoantibodies. "As a consequence, 82 collective targets of celastrol and AIH were identified, among which PIK3R1, SRC, MAPK1, AKT1, and HRAS exhibited a closer association with autoimmune hepatitis." (PMID 35359864, 2022).
Brooke-Spiegler syndrome (1 paper, 2025). Brooke-Spiegler syndrome (BSS) is an inherited predisposition syndrome presenting with skin appendage tumors, namely cylindromas, spiradenomas and trichoepitheliomas. "Trichoblastoma (TB) is a benign primitive follicular neoplasm that can occur in the setting of Brooke-Spiegler syndrome (CYLD mutations), in association with nevus sebaceous (mosaic HRAS mutations), or sporadically." (PMID 41203975, 2025).
carcinoid (1 paper, 2025). "This included HRAS (11p15) amplification on chromothriptic chromosome 11, KRAS (12q12) and ERBB3 (12q13) amplification on chromosome 12, as well as deletions of key carcinoid-associated tumor suppressor genes MEN1 (11q13) and ARID1A (1p36) on chromosomes 11 and 1, respectively." (PMID 39185963, 2025).
childhood cancers (1 paper, 2024). "Similarly, patients with Noonan and Costello (OMIM 218040) syndromes, caused by the PTPN11 and HRAS genes, have higher risk of childhood cancers, facial dysmorphia, cardiac disorders, neurocognitive delays, and musculoskeletal and cardiac abnormalities." (PMID 38534435, 2024).
chronic kidney disease (1 paper, 2019). Impairment of the renal function secondary to chronic kidney damage persisting for three or more months. "This study shows that cell proliferation, differentiation, apoptosis, migration (SRC, HRAS, HSP90AA1, CDK2), and ameliorating chronic kidney disease (MAPK14, F2, LCK, MMP9) appear to play important roles in the therapeutic effect of SQW." (PMID 31275142, 2019).
craniosynostosis (1 paper, 2024). Craniosynostosis is defined as the premature fusion of one or more cranial sutures leading to secondary distortion of skull shape resulting in skull deformities with a variable presentation. "Craniosynostosis has been described in individuals with pathogenic variants in other genes of the RAS/MAPK pathway including BRAF, KRAS, PPP1CB, SHOC2, PTPN11, RAF1, and HRAS." (PMID 37774117, 2024).
Dyskinesia (1 paper, 2021). A movement disorder which consists of effects including diminished voluntary movements and the presence of involuntary movements. "Another study showed that HRAS rs12628 is related to L-DOPA-induced dyskinesia (LID)." (PMID 34580608, 2021).
ectomesenchymoma (1 paper, 2025). An aggressive malignant mesenchymal neoplasm of the nervous system or soft tissues. "In our clinical setting, TT with MEK-inhibitor cobimetinib in a patient with ectomesenchymoma-harboring HRAS p.R61Q genetic variant leading to RAS–RAF–MEK pathway activation was unsuccessful." (PMID 41373618, 2025). "Similarly, HRAS p.Q61L in ectomesenchymoma was clinically accepted as a marker of sensitivity to MEK-inhibitor trametinib, but this therapy failed to provide a clinical benefit." (PMID 41373618, 2025).
enteritis (1 paper, 2023). Inflammation of the small intestine. "The four main active compounds of MCE involved in the treatment of enteritis are SAN, CHE, PRO, and ALL, and the five core targets are HSP90AA1, MAPK1, HRAS, JAK2, and AKT1." (PMID 37200837, 2023).
ependymoma (1 paper, 2019). A WHO grade II, slow growing tumor of children and young adults, usually located intraventricularly. "The specific variants we found in the present ependymoma case such as inTP53, HRAS, SMAD4, PIK3CA are not in TCGA projects." (PMID 32612806, 2019).
epithelial myoepithelial carcinomas of salivary glands (1 paper, 2025). "It is reported that epithelial myoepithelial carcinomas of salivary glands are characterized by a high incidence of HRAS mutations." (PMID 40243851, 2025).
ganglioneuroma (1 paper, 2022). A benign neuroblastic tumor of the sympathetic nervous system that occurs in childhood. "Importantly, these authors discovered that 20.0% (3/15) of the tumors studied by CP (PCC and ganglioneuroma) had BRAF mutations (K601E and K601N) and 46.7% (7/15) had HRAS mutations (Q61R, Q61L, G13R) based on genetic findings from the two cases studied by the NGS panel." (PMID 36187102, 2022).
germinoma (1 paper, 2016). A malignant germ cell tumor arising in the central nervous system. "We examined a total of 51 germinomas and 1 mixed GCT (germinoma and teratoma component) for mutations in KIT exons 11, 13, 17 and 18 as well as mutation hotspots in HRAS, KRAS, NRAS and RRAS-2." (PMID 27391150, 2016).
glaucoma (1 paper, 2023). Increased pressure in the eyeball due to obstruction of the outflow of aqueous humor. "Intriguingly, the results of this work have shed new light on the possible remarkable roles of AKT1, CXCL12, and HRAS genes in the pathogenesis of glaucoma." (PMID 36973823, 2023).
gynecological cancer (1 paper, 2019). "Similar results were also reported for AZD5363, although exclusive PIK3CA mutations did not correlate with increased response in another study in breast or gynecological cancer patients where concurrent mutations in KRAS, NRAS, HRAS, or BRAF were excluded." (PMID 31835495, 2019).
hemochromatosis (1 paper, 2018). A disorder of iron metabolism characterized by a triad of HEMOSIDEROSIS; LIVER CIRRHOSIS; and DIABETES MELLITUS. "Examples are mitogen-activated protein kinase (MAPK)/RAS family members (HRAS and NRAS), hemochromatosis (HFE), BRD7, ATM, vimentin (VIM), which are upregulated in poorly differentiated cell lines and in human HCC datasets." (PMID 30176945, 2018).
hypophosphatemic rickets (1 paper, 2025). Rickets due to low serum phosphate concentrations, the cause of which can be nutritional or genetic. "The use of monoclonal antibodies to fibroblast growth factor 23 (FGF23) was described as a therapy for hypophosphatemic rickets in a patient with a postzygotic c.182A > G mutation in the HRAS gene." (PMID 41438146, 2025). "At the same time, the presence of a mutation in the HRAS gene most often caused bone abnormalities, including hypophosphatemic rickets." (PMID 41438146, 2025). "At the same time, patients with HRAS mutations were more frequent to develop skeletal bone abnormalities, including hypophosphatemic rickets, than patients with KRAS mutations (65 vs. 27%, OR = 5.0, 95%CI = 1.4– 18.1, p = 0.015)." (PMID 41438146, 2025).
Immunodeficiency (1 paper, 2025). Failure of the immune system to protect the body adequately from infection, due to the absence or insufficiency of some component process or substance. "On the other hand, NRAS and HRAS appear less crucial; NRAS and HRAS knockout mice exhibited normal phenotypes and moderate immunodeficiency, respectively, indicating that these genes are not as widely expressed." (PMID 39857784, 2025).
Infertility (1 paper, 2026). "Screening via the STRING platform and Cytoscape 3.10.1 software yielded four core targets for ATBC-induced infertility-HSP90AA1, PIK3CA, CASP3, HRAS-and four core targets for icariin treatment-IL6, TNF, STAT3, and INS." (PMID 41898778, 2026).
Lynch syndrome (1 paper, 2017). An autosomal dominant hereditary neoplastic syndrome characterized by the development of colorectal carcinoma and a high risk of developing endometrial carcinoma, gastric carcinoma, ovarian carcinoma, renal pelvis carcinoma, and small intestinal carcinoma. "After excluding 30 Lynch syndrome cases, sporadic patients with CRC in our series shared similar mutation spectra in most CRC-associated genes between different age groups of patients, besides PTEN and HRAS mutation." (PMID 28678173, 2017).
malignant glioma (1 paper, 2017). A grade III or grade IV glioma arising from the central nervous system. "The HRas-shp53 transduced tree shrew invariably developed malignant gliomas, but not developed in the control group which expresses a shRNA against luciferase and EGFP instead of H-Ras." (PMID 28199986, 2017).
malignant phyllodes tumor (1 paper, 2023). A phyllodes tumor with sarcomatous stroma. "PIK3CA/KRAS and HRAS alterations have already been reported in borderline and malignant phyllodes tumors." (PMID 37240386, 2023).
mental disorder (1 paper, 2016). A disease that has its basis in the disruption of mental process.
metastatic squamous cell carcinoma (1 paper, 2021). A squamous cell carcinoma which has spread from its original site of growth to another anatomic site. "al found that epitope vaccines designed for HRAS mutations did not decrease tumor size because patients were already in late stages of metastatic squamous cell carcinoma." (PMID 35062725, 2021).
myoepithelial carcinoma (1 paper, 2025). "HRAS exon three mutations and a high percentage of EWSR1 rearrangements are commonly detected in clear cell subtype myoepithelial carcinoma." (PMID 39958930, 2025).
non-alcoholic fatty liver disease (1 paper, 2018). "Moreover, activating HRAS mutations were recently detected in HCC developed in mice with non-alcoholic fatty liver disease, which is increasingly recognized as promotor of hepatocarcinogenesis." (PMID 29423069, 2018). "Moreover, activating HRAS mutations have been described in a murine model of non-alcoholic fatty liver disease, i.e. a condition which is increasingly recognized as a major risk factor for HCC development and progression." (PMID 29423069, 2018).
non-alcoholic steatohepatitis (1 paper, 2025). "Moreover, up-regulated wild-type HRAS drove non-alcoholic steatohepatitis to HCC in mice." (PMID 41299786, 2025).
oesophageal cancer (1 paper, 2022). "HRAS mutations were known to be oncogenic; it was demonstrated in vitro that mutant HRAS hyperactivated MAPK and mTOR pathways in various cancer cell lines including lung, bladder, and oesophageal cancer." (PMID 35621690, 2022).
oral cavity cancer (1 paper, 2013). A primary or metastatic malignant neoplasm involving the oral cavity. "In previous studies, mutations in the HRAS gene were mainly detected in oral cavity cancer samples." (PMID 23718828, 2013).
oral cavity tumours (1 paper, 2018).
oropharyngeal carcinoma (1 paper, 2025). Carcinoma, predominantly squamous cell, arising from the epithelial cells of the oropharynx. "In the present study, the frequencies of HRAS mutations in p16-positive and p16-negative oropharyngeal carcinomas were almost the same." (PMID 40243851, 2025).
pancreatic NETs (1 paper, 2023).
parathyroid adenomas (1 paper, 2023). "Previous studies described the important role of the MAPK/ERK pathway in parathyroid cell function, and its dysregulation in parathyroid adenomas, where HRAS, ARAF, and MEK1 genes are up-regulated and ERK is hyperactivated." (PMID 37065733, 2023).
penile cancer (1 paper, 2013). A primary or metastatic malignant neoplasm that affects the penis. "A recent report showed a dysregulation of phosphatidylinositol 3-kinase and Ras pathways through somatic alterations of the PIK3CA, HRAS and KRAS genes in 11 out of 28 (39%) penile cancer samples, without any statistically significant difference between HPV-positive and HPV-negative cases." (PMID 23305393, 2013).
psoriasis (1 paper, 2023). An autoimmune condition characterized by red, well-delineated plaques with silvery scales that are usually on the extensor surfaces and scalp. "Despite the mounting evidence linking HRAS activity and psoriasis pathogenesis, there has been no reported case of human psoriasis associated with HRAS mutations to date." (PMID 39872300, 2023). "Previous studies revealed that increased expression of HRAS and enhanced GTP-binding activity of Ras can be observed in psoriasis patients’ skin." (PMID 39872300, 2023).
serous carcinomas (1 paper, 2015).
steatosis (1 paper, 2022). Increased lipid within the cytoplasm of cells. "In particular, the up-regulation of GTPase HRAS is associated with carcinoma, while up-regulation of Cortactin and down-regulation of YKT6 and DFFA are related to tumor cell invasiveness and down-regulation of PPIF/CypD may lead to steatosis." (PMID 36016316, 2022).
Wilms tumor (1 paper, 2008). An embryonal neoplasm characterized by the presence of epithelial, mesenchymal, and blastema components. "The authors claimed that they found new potential suppressors and oncogenes in Wilms tumor cells including HRAS and MUCDHL." (PMID 18564415, 2008). "However, (i) I found in PubMed that HRAS and MUCDHL have been already considered as the genes which are strongly associated with WT1 functions and Wilms tumor phenotype." (PMID 18564415, 2008).
cancer (678 papers, 1994 to 2026). A tumor composed of atypical neoplastic, often pleomorphic cells that invade other tissues. "Mutations in KRAS, NRAS, and HRAS are among the most frequent oncogenic alterations in human cancers." (PMID 41196374, 2025). "Deletion of NRAS or HRAS have shown to cause either a tumor promoting or tumor suppressive effect dependent of the type of cancer." (PMID 40596921, 2025). "NRAS mutations are frequently observed in melanomas and certain hematopoietic malignancies, while HRAS mutations are prevalent in head and neck cancers." (PMID 40906088, 2025). "The three Ras genes (KRAS, NRAS, and HRAS) are frequently mutated in cancer (11%, 3%, and 1% of cancers in the US, respectively), and the corresponding proteins are active when localized to the membrane." (PMID 39995872, 2025). "The Cancer Genome Atlas and other studies have identified HRAS, CASP8, and NOTCH1 mutations in human papillomavirus-negative, EGFR-negative HNSCC." (PMID 41463200, 2025). "At the same time, patients with the HRAS G13R mutation developed malignant neoplasms much more frequently than other patient groups." (PMID 41438146, 2025). "Among different RAS isotypes, KRAS is the prevalent mutation associated with different types of cancer, namely, pancreatic, colorectal, and lung carcinoma, while the incidence of NRAS and HRAS mutation is less among these three types of cancer." (PMID 39056802, 2024). "Of the oncogenic mutations in the RAS family, the KRAS locus is the most often affected with a relatively higher prevalence in about 30% of cancerous tumors, while the HRAS and NRAS locus mutations are present in a modest 8% and 3%, respectively." (PMID 39184150, 2024). "The three main RAS genes that are frequently mutated in human cancers include Harvey rat sarcoma viral oncogene homolog (HRAS), Kirsten rat sarcoma viral oncogene homolog (KRAS), and Neuroblastoma ras viral oncogene homolog (NRAS)." (PMID 38982514, 2024). "Hyper-methylated genes included previously reported targets of recurrent hyper-methylation in OSCC, such as DDAH2, CCNA1, DCC, as well as some cancer-associated genes including HRAS." (PMID 38589501, 2024). "Mutations in the hRAS gene have been connected to a variety of diseases, such as cancer and developmental issues." (PMID 38420094, 2024). "Downregulation of HRAS has been linked to lower aggressiveness and reduced cell proliferation in certain types of cancer." (PMID 39349928, 2024). "Although these mutations had been reported as cancer genes, all except HRAS p.Q61 were uncommon mutations." (PMID 38172600, 2024). "The hRAS gene variations have been linked to several illnesses, including cancer and developmental disorders." (PMID 38420094, 2024). "Genetic alterations in RAS genes, notably in HRAS, are among the most common mutations detected in human cancers." (PMID 37153521, 2023). "NRAS and HRAS are proto-oncogenes involved in cell division; thus, their mutations can lead to uncontrolled proliferation, a feature of cancer cells." (PMID 38137511, 2023). "Three rat sarcoma (RAS) gene isoforms, KRAS, NRAS, and HRAS, constitute the most mutated family of small GTPases in cancer." (PMID 37662925, 2023). "HRAS-mutant cancers had a higher frequency of co-altered mutations (48.8%) in MAPK, PI3K, or RTK pathways genes compared to KRAS- and NRAS-mutant cancers (41.4% and 38.4%, respectively; p < 0.05)." (PMID 37503077, 2023). "Our study is significant because mutations in HRAS are associated with various diseases, including cancer." (PMID 37153521, 2023). "RAS genes are frequently mutated across cancer types; however it has been reported that HRAS mutations are relatively low frequency overall, and associated primarily with squamous cancers." (PMID 37638000, 2023). "HRAS gene provides the instructions for making the HRAS protein that plays an important role in regulating cell division and when the HRAS gene gets mutated it gets involved in initiating cancer." (PMID 37868370, 2023).